KRAS (KRas proto-oncogene, GTPase)
Diseases named in the same sentence as KRAS in open-access papers (continued):
Sharing a sentence is not in itself a finding about the gene and the disease.
colorectal cancer (continued). "Given that KRAS p.G12C protein variant inhibitors can be an effective treatment strategy for advanced colorectal cancer, our study is likely of clinical relevance." (PMID 39039804, 2024). "Colorectal cancer with PIK3CA mutations often accompanies mutations in genes such as KRAS, BRAF, PTEN, AKT1, all of which are components of the PI3K signaling pathway or MAPK signaling pathway." (PMID 39555098, 2024). "KRAS is the most common mutated gene in cancer, and KRAS mutation is a known driving factor in three of the deadliest cancers: lung cancer, colorectal cancer, and pancreatic cancer." (PMID 38309290, 2024). "In colorectal cancer with KRAS gene mutations, tumor cells take up more copper through macro-pinocytosis, which promotes tumor growth." (PMID 38662225, 2024). "In colorectal cancer, KRAS mutation has been reported as an unfavorable prognosis factor, though the literature data are somewhat mixed likely due at least in part to the presence/absence of the adjustment for a strong confounder variable, BRAF mutation." (PMID 39039804, 2024). "The first 3 clusters, corresponding to non-small cell lung cancer, pancreatic cancer, and colorectal cancer, indicate that the bulk of research involving KRAS mutations centers on these 3 tumor types." (PMID 39252322, 2024). "Mutations in the PIK3CA and KRAS genes are commonly found in colorectal cancer and are associated with increased tumor risk." (PMID 38898987, 2024). "The activation of PI3K/AKT as an escape mechanism to vertical suppression of the EGFR/RAS/MAPK pathway by EGFR and MEK inhibitors in KRAS-mutant colorectal cancer has also been reported and is linked to drug resistance and disease recurrence." (PMID 38409090, 2024). "This study explores and verifies potential molecular targets through which KRAS mutations regulate the colonization of Fusobacterium nucleatum (FN) in colorectal cancer (CRC)." (PMID 39462261, 2024). "Even though the incidence of KRAS mutations is significant in colorectal cancer (30–50%), it occurs far more frequently in pancreatic cancer (~90%)." (PMID 38891084, 2024). "Similar to colorectal cancer and synovial sarcoma, the Wnt pathway is very important for the occurrence and development of PCa, and KRAS mutations also occur in PCa." (PMID 38226156, 2024). "In KRAS-mutated colorectal cancer, the most frequent mutations in Group 1 were KRAS G12V or G12D, whereas in Group 4, most common were KRAS G13D or G12D." (PMID 38282550, 2024). "This was tested as a monotherapy and in combination with pembrolizumab (anti PD-1) in patients with KRAS-mutated advanced or metastatic non-small cell lung cancer, colorectal cancer, and pancreatic cancer." (PMID 39329989, 2024). "Compared to other sub-types of colorectal cancer, a higher proportion of patients with dMMR and KRAS mutations were observed." (PMID 38229035, 2024). "KRAS mutations frequently occur in cancers, particularly pancreatic ductal adenocarcinoma, colorectal cancer, and non-small cell lung cancer." (PMID 38992694, 2024). "KRAS is one of the most prominent driver genes implicated in colorectal cancer (CRC), with mutations detected in 33% to 50% of CRC patients." (PMID 39001385, 2024). "Clinicopathological, molecular, and microbial characteristics according to KRAS mutation status in 1347 colorectal cancer cases." (PMID 39039804, 2024). "This case report presents a unique instance of colorectal cancer brain metastasis harboring both KRAS and BRAF mutations, highlighting its clinical significance and therapeutic challenges." (PMID 39385899, 2024).
colorectal cancer (continued). "In our dataset, in addition to the c.34G>T (p.G12C) mutation (shown by the current study), KRAS c.34G>C (p.G12R) and c.35G>T (p.G12V) mutations were associated with higher colorectal cancer‐specific mortalities among various KRAS mutations." (PMID 39039804, 2024). "MEK1/2 inhibitors (AS703026 and AZD6244) are potential approaches for KRAS-mutated colorectal cancer resistant to EGFR monoclonal therapy." (PMID 38844562, 2024). "In both lung cancer and colorectal cancer, the KRAS mutation pattern is quite heterogeneous between the primary tumor and the corresponding metastases." (PMID 39201772, 2024). "Increased ATP7A expression protects against excessive copper-induced toxicity in colorectal cancer cells with a mutation in the KRAS gene." (PMID 39408933, 2024). "Kirsten-rat-sarcoma viral oncogene homolog (KRAS) is the most common mutation driving factor, accounting for 15–30% of all human malignant tumors, and KRAS mutations are particularly common in pancreatic ductal adenocarcinoma, colorectal cancer, and NSCLC." (PMID 38734764, 2024). "Its safety and tolerability is currently being studied in patients with NSCLC, colorectal cancer, pancreatic cancer, and other solid tumors with documented KRAS G12D mutations in a phase I trial." (PMID 39337530, 2024). "KRAS mutations are more common in pancreatic adenocarcinomas, colorectal cancer, and non-small-cell lung cancer." (PMID 39451209, 2024). "For instance, the hypermethylation of the O-6-methylguanine-DNA methyltransferase (MGMT) gene, which encodes a DNA repair protein, precedes KRAS mutations in the onset of colorectal cancer, even when mutations in KRAS are early events in carcinogenesis." (PMID 38893242, 2024). "The RAS gene is also an important target for colorectal cancer treatment, and KRAS mutation status can predict the therapeutic effect of anti‐epidermal growth factor (EGFR)." (PMID 38698687, 2024). "PI3K mutations are relatively common in colorectal cancer, but there are very few pancreatic or lung KRAS mutant tumors harboring genetic mechanisms for PI3K pathway activation." (PMID 39025835, 2024). "In pancreatic cancer, the rate of KRAS mutation is >80%, while in lung or colorectal cancer, it is ~30%." (PMID 38473821, 2024). "Validating these findings is further needed for the benefit of colorectal cancer patients with KRAS mutations in research and clinical trials." (PMID 38844562, 2024). "The Cancer Genome Atlas also indicated KRAS mutant colorectal cancer (CRC) are closely associated with decreased immune infiltration and reactivity." (PMID 38216551, 2024). "For instance, approximately 30%–50% of colorectal cancer tumors have a mutated KRAS gene, whereas it has been observed to be mutated in 90% of pancreatic cancers of all grades, and the mutation signatures differ between them as well." (PMID 39441719, 2024). "Inhibiting either BCAM or laminin α5 can disturb the adhesion between colorectal cancer cells harboring KRAS mutations and endothelial cells." (PMID 39000374, 2024). "KRAS A146 mutations are primarily found in colorectal cancer and are rarely reported in other types." (PMID 38668053, 2024). "For instance, quercetin suppresses the Notch-1 signaling pathway, which lowers the proliferation of colon cancer cells and colon cancer stem cells and selectively generates the KRAS mutations that cause apoptosis in colorectal cancer cells." (PMID 39201782, 2024). "Of KRAS oncogenic mutations, KRAS c.34G>T (p.G12C) mutation occurs in 3%–4% of colorectal cancer patients." (PMID 39039804, 2024).
colorectal cancer (continued). "Despite KRAS mutations being more commonly observed in colorectal cancer, these studies revealed a noteworthy connection between the onset of abnormal tissue growth and the formation of distant metastases, promoting the development of secondary tumors." (PMID 38397135, 2024). "Mutations in both BRAF and KRAS are thought to be mutually exclusive in cases of colorectal cancer despite BRAF's involvement in the KRAS signaling pathway." (PMID 39467702, 2024). "Survival analyses of 1112 BRAF‐wild‐type colorectal cancer patients according to the KRAS mutation status." (PMID 39039804, 2024). "For instance, left-sided colorectal cancers are commonly associated with KRAS and BRAF mutations, whereas right-sided cancers are more linked to microsatellite instability and CpG island methylation anomalies." (PMID 38711918, 2024). "We examined the prognostic role of KRAS mutation within 1122 BRAF‐wild‐type colorectal carcinoma cases." (PMID 39039804, 2024). "KRAS G12C mutations occur mainly in lung carcinomas obtained from smokers as well as in colorectal carcinomas, although they are occasionally present in other cancer types." (PMID 38612902, 2024). "In conclusion, this study provides novel evidence for clinical and tumor characteristics of KRAS c.34G>T (p.G12C)‐mutated colorectal carcinoma, which needs to be replicated by independent datasets." (PMID 39039804, 2024). "Our study provides novel evidence for clinical and tumor characteristics of KRAS c.34G>T (p.G12C)‐mutated colorectal carcinoma." (PMID 39039804, 2024). "We found the unique association of KRAS c.34G>T‐mutated colorectal carcinoma with both CIMP‐high (when compared with other KRAS‐mutated tumors) and CIMP‐low statuses (when compared with KRAS‐wild‐type tumors)." (PMID 39039804, 2024). "KRAS variants are common in both colorectal pre-cancer and cancer, with reported KRAS mutation frequencies of 32.4% in adenomas and 45.5% of colorectal carcinomas." (PMID 39512764, 2024). "We utilized a prospective cohort incident tumor biobank (including 1347 colorectal carcinomas) and detected KRAS c.34G>T (p.G12C) mutation in 43 cases (3.2%) and other KRAS mutations (in codon 12, 13, 61, or 146) in 467 cases (35%)." (PMID 39039804, 2024). "The clinicopathological features of KRAS c.34G>T (p.G12C)‐mutated colorectal carcinomas, in particular, differences from those from other KRAS‐mutated carcinomas remain to be characterized." (PMID 39039804, 2024). "KRAS mutations, which are present in approximately 40% of colorectal carcinomas, have been implicated in tumor development, progression, treatment resistance, and recurrence." (PMID 39039804, 2024). "Previous studies have shown potential interrelated links between cecal location, KRAS mutation, and F. nucleatum in colorectal carcinomas." (PMID 39039804, 2024). "This study aimed at determining the frequency of BRAF V600E and KRAS exon 2,3,4 mutations in colorectal carcinoma patients at the Aga Khan University Hospital Nairobi, Kenya." (PMID 39364024, 2024). "Recently, it has been demonstrated that VC at pharmacological plasma concentrations, acquired intravenously, can selectively kill KRAS- or BRAF-mutated colorectal cancer cells by targeting GAPDH." (PMID 36787291, 2023). "In colorectal cancer, KRAS mutations occur in 50.4% of cases, NRAS mutations in 4.2%, and HRAS in 0.5%." (PMID 37240418, 2023). "KRAS mutation is documented in colorectal cancer in a very large number of patients, close to half of the cases, and it is considered a predictor of poor outcome." (PMID 36836752, 2023). "Codon 12 of KRAS, such as G12V, G12D, G12C, etc, has the highest mutation frequency in pancreatic cancer, colorectal cancer and non-small cell lung cancer, accounting for about 90% of all KRAS mutations." (PMID 37287989, 2023). "The authors demonstrated that Fn is enriched in colorectal cancers exhibiting the SSP phenotype, and in colorectal cancers carrying KRAS mutations." (PMID 37772997, 2023).
colorectal cancer (continued). "This study examined the effect of reovirus treatment of KRAS-mutated colorectal cancer and if it has an effect on the CRC cell ncRNA and microRNA profile." (PMID 37873786, 2023). "While KRAS active mutations are required for the development of many cancer types including non-small-cell lung carcinoma, colorectal cancer, and PDAC40." (PMID 37488138, 2023). "The KRAS gene is often mutated at codons 12 and 13 and is an unfavorable factor in the development, progression, and prognosis of colorectal cancer." (PMID 37008032, 2023). "Based on the inclusion and exclusion criteria, 225 patients were divided according to their KRAS status between Arm A (88 patients with one or more KRAS mutations) and Arm B (137 patients with KRAS wild-type colorectal cancer)." (PMID 37761297, 2023). "This process triggers cell death in colorectal cancer cells harboring refractory KRAS gene mutations." (PMID 38264357, 2023). "For patients with colorectal cancer with liver metastases, it is important to determine the genetic mutations (e.g., KRAS mutations) of the liver metastases." (PMID 38067353, 2023). "The quantity of Fn in colorectal cancer with MSI-H or MLH1 hypermethylation is higher than in colorectal cancer with KRAS mutations." (PMID 37772997, 2023). "Both radiomics and radiogenomics have shown promising results in predicting treatment response, nodal status, and metastasis in colorectal cancer, as well as the potential for KRAS mutations." (PMID 37761253, 2023). "Among them, KRAS G12V and G12D mutations are the most common, accounting for about 60% of pancreatic cancer, 20% of colorectal cancer, and 8% of non-small cell lung cancer." (PMID 37287989, 2023). "Comprising 33% of lung, 91% of pancreatic, and 42% of colorectal cancers, KRAS mutations directly contribute to one million deaths annually worldwide." (PMID 37925476, 2023). "We present preclinical efficacy data of statins; statins effectively enhanced antitumor effect of L-OHP in KRAS-mutated colorectal cancer and suppressed L-OHP-induced neuropathy." (PMID 37069612, 2023). "In this study, seven common KRAS mutations that are frequently observed in pancreatic and colorectal cancers were genotyped and are expected to be applied to predict the applicability and efficacy of KRAS-targeted drugs." (PMID 36810451, 2023). "KRAS mutation in colorectal cancer drives immune evasion by sensitizing cytotoxic T‐cells to activation‐induced cell death through lactic acid‐mediated NF‐κB inactivation, and thus impairs immunotherapeutic efficacy." (PMID 36599679, 2023). "Among TMEMs, TMEM211 is differently expressed between KRAS G12 mutated and wild-type colorectal cancer." (PMID 37367036, 2023). "BRAF V600E and KRAS mutations that occur in colorectal cancer (CRC) define a subpopulation of patients with an inferior prognosis." (PMID 37240418, 2023). "Rac1b overexpression is also associated with poor outcome of wide-type KRAS/BRAF colorectal cancer treated with FOLFOX/XELOX chemotherapy." (PMID 37373047, 2023). "About 60%-80% of KRAS mutations are found to be G12V and G12D in pancreatic cancer, and 20%-30% in colorectal cancer." (PMID 37287989, 2023). "It is worthwhile to investigate the anticancer activity of Cu E in colorectal cancer and pancreatic ductal adenocarcinoma, given that KRAS mutations are prevalent in these malignancies." (PMID 37886957, 2023). "In colorectal cancers, despite the presence of KRAS, NRAS and BRAF mutations in 50–60% of cancer patients, phospho-ERK staining was detectable in less than 10% of the cells." (PMID 38201521, 2023).
colorectal cancer (continued). "Several studies have shown the association between SNVs present in the 3′UTR region of the KRAS gene and various types of cancer, including breast cancer, Wilms tumors, colorectal cancer, and glioma, among others." (PMID 37566020, 2023). "Previous studies have shown that statins, 3-hydroxy-3-methylglutaryl coenzyme A reductase inhibitors, are effective to treat KRAS mutated colorectal cancer cells." (PMID 37069612, 2023). "Kirsten rat sarcoma (KRAS) mutation, occurring in 30–40% of colorectal cancers, has been reported to play a potential role in colorectal cancer tumour development." (PMID 38087207, 2023). "KRAS is a target of particular interest because of its role as an oncogene in the gut, where up to 50% of colorectal cancers harbor a KRAS mutation." (PMID 37883185, 2023). "Binimetinib is a MEK 1/2 inhibitor that has shown clinical therapeutic efficacy against KRAS-mutated cancers such as acute myeloid leukemia, colorectal cancer, melanoma, and NSCLC, especially when in combination with other drugs." (PMID 37376135, 2023). "It has been reported that KRAS mutations in patients with colorectal cancer receiving FOLFOX-4 therapy were involved with shorter overall survival (OS) and disease-free survival (DFS)." (PMID 37069612, 2023). "We categorized tumors with APC wild-type and BRAF or KRAS mutation as serrated, a subtype of colorectal cancer that derive from serrated polyps via an alternate pathway usually with absence of APC mutation." (PMID 37057593, 2023). "KRAS mutations are associated with an immunosuppressive microenvironment in patients with colorectal cancer (CRC)." (PMID 37542037, 2023). "Exogenous rLGALS9, a lysosome inhibitor, exhibits high cytotoxicity against KRAS-mutated colorectal cancer cells." (PMID 38264357, 2023). "In a 190 colorectal cancer cohort, we identified seven somatic mutations in KRAS, NRAS and BRAF as well as five MSI loci (D2S123/D5S346/D17S250/BAT‐25/BAT‐26) simultaneously." (PMID 36583506, 2023). "Prenylation promotes KRAS, one of the most frequently mutated genes in colorectal cancer, transforming from GDP-bound inactive state into GTP-bound active state anchored in plasma membrane, then initiating downstream signaling." (PMID 37138847, 2023). "We found KRAS mutation in colorectal cancer drove immune evasion by sensitizing cytotoxic T‐cells to activation‐induced cell death via lactic acid‐mediated NF‐κB inactivation, and impaired the efficacy of anti‐PD‐1 and adoptive T‐cell therapy." (PMID 36599679, 2023). "In a mouse model of colorectal cancer, tumor cells with Kirsten rat sarcoma viral oncogene homolog (KRAS) gene mutations can use macropinocytosis to acquire more copper, which seems to be essential for supporting tumor growth." (PMID 37427098, 2023). "Colorectal cancer (CRC) is a significant global health issue characterized by a high prevalence of KRAS gene mutations." (PMID 37504287, 2023). "KRAS is a predictive biomarker for colorectal cancer; mutations occurring to KRAS in somatic cells are related to low response to anti-EGFR-mediated treatment." (PMID 36979610, 2023). "Previously, studies have conflicted in regard to the impact of KRAS mutation on prognosis in colorectal cancer." (PMID 37190303, 2023). "Our research focuses on establishing connections between the expression levels of sphingolipid-related genes expression levels and both KRAS mutations and various clinicopathological characteristics in patients diagnosed with colorectal cancer (CRC)." (PMID 37758931, 2023). "KRASG12D is a more prevalent KRAS mutation type that is found in various cancers, including pancreatic cancer, colorectal cancer, and lung adenocarcinoma." (PMID 37669923, 2023). "Mutation and activation of the KRAS gene in the human body are important causes of the development and progression of colorectal cancer." (PMID 37008032, 2023).